ERCC1 (ERCC excision repair 1, endonuclease non-catalytic subunit)
Diseases named in the same sentence as ERCC1 in open-access papers (continued):
Sharing a sentence is not in itself a finding about the gene and the disease.
ovarian carcinoma (continued). "However, more comprehensive studies with larger independent cohorts should be performed to unveil the real relationship between these significant genetic variations in the ERCC1, XPC and ERCC2 and ovarian cancer risk." (PMID 29669843, 2018). "The result showed that both ERCC1 rs11615 and XPC rs2228000 were significantly associated with reduced risk of ovarian cancer under dominant genetic model (adjusted OR = 0.35, 95% CI = 0.20–0.61, P=0.0002 and adjusted OR = 0.49, 95% CI = 0.30–0.81, P=0.005 respectively)." (PMID 29669843, 2018). "In the present study, we performed a hypothesis-based association to explore the impact of SNPs in these core genes (XPA, XPC, XPG, ERCC1, ERCC2, and ERCC4) on the risk of ovarian cancer by genotyping a pool of 17 SNPs in 89 patients and 356 controls." (PMID 29669843, 2018). "In conclusion, our results indicated that ERCC1, XPC and ERCC2 might influence ovarian cancer susceptibility." (PMID 29669843, 2018). "ERCC1 exon VIII alternative splicing can also regulate cisplatin-resistance in ovarian cancer." (PMID 29156754, 2017). "Nevertheless, ERCC1 marks a subpopulation of CTCs which might be useful for monitoring platinum-based chemotherapy and for assessing post-therapeutic outcome of ovarian cancer patients." (PMID 28388557, 2017). "So far, any functional characteristics of ERCC1-expressing CTCs in the blood of ovarian cancer patients are unknown." (PMID 28388557, 2017). "In addition, the ratios of larger ERCC1 to total ERCC1 mRNA following cisplatin treatment in ovarian cancer cells PEO14 and A2780 indicated increases from 41% to 98% and 54% to 79% respectively." (PMID 29156754, 2017). "Specifically, we suggest that ERCC1+CTCs could additionally be useful as a surrogate for monitoring platinum-based chemotherapy and to assess the post-therapeutic outcome of ovarian cancer." (PMID 28388557, 2017). "Based our data, the novel larger ERCC1 transcript maybe the main ERCC1 transcript involved in the regulation of ovarian cancer cells resistance to chemotherapy." (PMID 29156754, 2017). "All together, our data suggested that the novel larger ERCC1 transcript may be related to cellular resistance to cisplatin for ovarian cancer patients." (PMID 29156754, 2017). "We recently showed that the presence of ERCC1+CTCs (circulating tumor cells) at primary diagnosis of ovarian cancer, a potentially platinum-resistant CTC-subgroup, is an independent predictive biomarker for primary platinum-resistance and poor prognosis of ovarian cancer." (PMID 28388557, 2017). "In ovary cancer cell, Tan-IIA induced apoptosis, reduced cisplatin resistance in COC1/DDP cells, and caused significant growth inhibition through p38-mediated down-regulation of survivin, ERCC1 and LRP mRNA expression." (PMID 25192287, 2014). "There is a clinical study showing that paclitaxel may help alleviate ERCC1-related platinum resistance in ovarian cancer." (PMID 24053422, 2013). "β-Elemene significantly attenuated the cisplatin-induced increase in the ERCC-1 protein level in A2780/CP70 ovarian cancer cells, indicating that the reduction of DNA repair activity by β-elemene is positively associated with increased cisplatin cytotoxicity in resistant ovarian tumor cells." (PMID 23817665, 2013). "In clinical practice, clinicians may prefer to select chemotherapy schemes other than platinum containing chemotherapy for patients with ERCC1 polymorphism rs11615 TT genotype, such as early use of PARP inhibitors and anti-angiogenesis, especially in ovarian cancer." (PMID 37141338, 2023). "Other studies document that quantification of ERCC1 (excision repair cross-complementation group 1) or cyclophilin 3 expression in iCTCs might be used to monitor platinum resistance and post-therapeutic outcome of ovarian cancer patients." (PMID 36551515, 2022).
ovarian carcinoma (continued). "ERCC1 gene is the dominant gene in NER and an important component of DNA damage identification and repair, of which the expression and single nucleotide polymorphism may affect platinum resistance and prognosis in patients with ovarian cancer." (PMID 34148553, 2021). "Therefore, research to investigate the association of ERCC1, XRCC1 and GSTP1 polymorphisms with clinical treatment responses and adverse events from platinum-based chemotherapy especially in Thai patients with advanced epithelial ovarian cancer was needed." (PMID 32711417, 2020). "Thus ERK activation may play an important role in the regulation of larger ERCC1 induction by cisplatin in ovarian cancer cells." (PMID 29156754, 2017). "Therefore, we probed whether the MAPK pathway activation was responsible for induction of the larger ERCC1 transcript in ovarian cancer cells following cisplatin treatment." (PMID 29156754, 2017). "Larger ERCC1 expression may be related to cisplatin resistance in ovarian cancer cells." (PMID 29156754, 2017). "Further investigations on the functions of the larger ERCC1 transcript indicated that overexpression of the larger ERCC1 transcript in ovarian cancer cells could increase cell viability and stimulate colony formation to protect ovarian cancer cells from cisplatin induced DNA damage." (PMID 29156754, 2017). "We have previously shown that upon stimulation with cisplatin, JNK may directly phosphorylate c-Jun at serine residues 63 and 73 to activate ERCC-1 transcription via AP-1 in A2780/CP70 ovarian cancer cells, which would place ERCC-1 under the influence of the JNK/Ras/AP-1 signal transduction pathway." (PMID 23817665, 2013). "The in vitro, in vivo, and clinical studies have demonstrated that high expression of ERCC1 correlates with cisplatin resistance in multiple tumors while knock-down of ERCC1 expression enhances the cisplatin cytotoxicity in cisplatin-resistant ovarian cancer cells." (PMID 21385444, 2011). "Decreased levels of ERCC1–XPF correlated not only with improved progression-free survival but also increased platinum and PARP inhibitor sensitivity in patient samples of ovarian cancer tissue." (PMID 36551731, 2022). "A similar increase in expression was observed for both excision repair cross-complementing group 1 (ERCC1) and XPA in platinum-resistant ovarian cancer tissues." (PMID 36551731, 2022). "This study examined the mRNA expression levels of HSF1, HSP70, MDR1 and ERCC1 by RT‐qPCR in SKOV3, SKOV3/DDP, COC1, COC1/DDP and human primary ovarian cancer cells, of which MDR1 and ERCC1 are important drug-resistance genes." (PMID 34539881, 2021). "The mRNA levels of endonuclease ERCC1 and helicase XPB (ERCC3), key players in the NER pathway, tend to be higher in OCCC as compared to other types of ovarian cancers." (PMID 34737943, 2021). "Western blotting was used to analyze HSF1, HSP70, MDR1 and ERCC1 proteins, which are related to HSF1/HSP70 signaling pathway in SKOV3, SKOV3/DDP, COC1, COC1/DDP and human primary ovarian cancer cells." (PMID 34539881, 2021). "In particular, the correlation between the expression of ERCC1 and ERCC2 in 42 Ovarian cancer patient-derived xenografts (PDX), as measured by quantitative RT-PCR, was r = 0.71, p-value = 1.4 × 10−7." (PMID 34837938, 2021). "ERCC1 is the protein most investigated as a read-out of NER repair in different tumor types, including ovarian carcinoma, but with very contrasting results." (PMID 32847049, 2020). "Thus, to investigate whether the mechanism by which β-elemene reverses drug resistance to cisplatin involves, at least in part, the inhibition of DNA repair activity, we tested the effect of β-elemene on cisplatin-upregulated ERCC-1 expression in resistant ovarian cancer cells." (PMID 23817665, 2013). "In ovarian cancer, ERCC4 mRNA expression has previously been shown to be tightly correlated with ERCC1 mRNA expression, indicating that the mechanisms regulating the expression of these genes are linked." (PMID 24144331, 2013).
ovarian carcinoma (continued). "Although immunohistochemistry of ERCC1 protein in primary tumors did not predict platinum resistance, ERCC1(+) CTCs did predict platinum resistance at the primary diagnosis of ovarian cancer." (PMID 39219215, 2024). "Cisplatin-resistant TSCC is known to exhibit increased expression of excision repair cross complementation group 1 (ERCC1), a key component of the NER pathway, and previous studies have shown that silencing ERCC1 reverses resistance to cisplatin in gastric and ovarian cancers." (PMID 35204785, 2022). "We investigated the role of the NER proteins—ERCC1, XPF, ERCC1/XPF complex—and of the BER protein DNA polymerase β, as possible biomarkers of cisplatin (DDP) response in a platform of recently established patient-derived ovarian carcinoma xenografts (OC-PDXs)." (PMID 32847049, 2020). "Focusing on high-grade serous/endometrioid PDXs, as they account for 80% of ovarian carcinomas and the majority of our OC-PDX samples, only the correlation between the ERCC1 IHC-score with XPF mRNA was maintained (Spearman correlation coefficient 0.69, p = 0.0001)." (PMID 32847049, 2020). "Therefore, we conducted genotyping for 17 SNPs of six NER core genes (XPA, XPC, XPG, ERCC1, ERCC2, and ERCC4) in 89 ovarian cancer cases and 356 cancer-free controls." (PMID 29669843, 2018). "Lack of correlation between ERCC1 mRNA and protein levels in ovarian cancers has also been reported, suggesting that there is not a simple direct relationship between ERCC1 mRNA levels and DNA repair capacity." (PMID 28903417, 2017). "Independent of ERCC1 assessment, we previously confirmed the negative prognostic impact of CTCs before surgery and after chemotherapy, as detected by the AdnaTest Ovarian Cancer." (PMID 28388557, 2017). "In ovarian cancer, ERCC1 appears not to frequently undergo copy number aberrations, whereas it is a more common phenomenon in glioma (note: blotting-based method were applied in both studies)." (PMID 24144331, 2013). "Our thorough evaluation of the NER protein levels (XPA, XPC, XPF, XPG, ERCC1, and DDB2) and corresponding mRNA levels in various cisplatin-sensitive and -resistant ovarian cancer cell lines revealed that the transcript levels of various NER factors do not accurately reflect their protein levels." (PMID 21385444, 2011). "Most importantly, despite ERCC1 function correlating with chemotherapy response in carcinoma (e.g. lung, bladder, ovarian cancers), only non-carcinoma (melanoma or sarcoma) cell lines were used in the two previous studies focusing on ERCC1 degradation/ubiquitylation." (PMID 38272916, 2024). "We demonstrated that platinum resistance, which is mediated by cisplatin-induced ERCC-1, MRP-2, and XIAP in SKOV3 ovarian cancer cells (with a moderate level of HOXB9 expression), could be overcome by cisplatin treatment alone through the inhibition of Bcl-2 and activation of Bax." (PMID 36674764, 2023). "We now explored in more detail, in how far the auxiliary assessment of ERCC1-transcripts influences overall CTC-detection rate and whether this molecular marker may improve the phenotypic range of CTC-detection by the AdnaTest Ovarian Cancer platform." (PMID 28388557, 2017). "In conclusion, the platinum resistance of SKOV3 ovarian cancer cells may be different in terms of its refractoriness to cisplatin treatment according to the level of HOXB9 overexpression and the subsequently induced expression of ERCC-1, MRP-2, and XIAP, as well as Bcl-2/Bax expression." (PMID 36674764, 2023). "Therefore, we could not demonstrate a predictive role of ERCC1 levels for platinum resistance in ovarian cancer." (PMID 35147976, 2022). "Therefore, it was speculated that PGPIPN may regulate HSF1/HSP70 signal transduction and alter the expression level or activity of proteins in human ovarian cancer cells, which leads to the reduction of MDR1 and ERCC1 expression, thereby increasing the sensitivity of ovarian cancer cells to DDP." (PMID 34539881, 2021).
ovarian carcinoma (continued). "This novel ERCC1 transcript may therefore not be specific to ovarian cancer cells." (PMID 29156754, 2017).
colorectal cancer (58 papers, 2003 to 2025). A primary or metastatic malignant neoplasm that affects the colon or rectum. "In this merged analysis, we demonstrated that the susceptible risk of colorectal cancer was associated with the TT variant of ERCC1 Asn118Asn (rs11615) and TC heterozygote compared to wild-type CC homozygote in the overall population." (PMID 36277013, 2022). "The altered expression of ERCC genes has been associated with increased risk of colorectal cancer, where ERCC1, ERCC2 and ERCC5 were overexpressed, and invasive cervical carcinoma, where ERCC1 and ERCC2 were underexpressed." (PMID 35955506, 2022). "This meta-analysis is an attempt to analyze the potential correlation between the genetic variant of ERCC1 rs11615 and colorectal cancer as well." (PMID 36277013, 2022). "With those limitations in mind, our meta-analysis results indicated that ERCC1 rs11615 polymorphism carrying T variant had an association with colorectal cancer in Asians and are still credible." (PMID 36277013, 2022). "Previous studies have shown that single nucleotide polymorphisms of ERCC1 contribute to the susceptibility of colorectal cancer patients to L-OHP." (PMID 33014113, 2020). "In colorectal cancer the expression of ERCC1 has been associated with poor survival and poor response to 5-FU and oxaliplatin combination chemotherapy in metastatic CRC patients." (PMID 32244885, 2020). "We sought to ascertain if ERCC1 expression dynamics and a single nucleotide polymorphism (SNP) rs11615 are biomarkers of sensitivity to oxaliplatin therapy in patients with colorectal cancer (CRC)." (PMID 31565185, 2019). "Another example corresponds to SNP rs11615 in the gene ERCC1, which was associated with colorectal cancer, where the pause propensity change is also large, against a small change in the relative synonymous codon usage." (PMID 28289571, 2017). "For example, various studies have focused on the relationship between ERCC1 polymorphisms and prognosis for the treatment with platinum agents in colorectal cancer patients." (PMID 25253066, 2014). "Inherited variation in XPD and ERCC1 was associated with outcome in patients with colorectal cancer in Taiwan." (PMID 23429196, 2013). "For example, low gene expression levels of the NER protein ERCC1 were associated with superior response to 5-FU/cisplatin in gastric cancer and 5-FU/oxaliplatin in colorectal cancer." (PMID 15213713, 2004). "We wanted to confirm whether ERCC1 rs11615 could serve as a marker for genetic susceptibility to colorectal cancer." (PMID 36277013, 2022). "Emerging epidemiological studies have indicated that the presence of colorectal cancer (CRC) may be relevant to the ERCC1 rs11615 genetic polymorphism." (PMID 36277013, 2022). "Our data from regulatable HCT116-Tet-on and COLO205-Tet-on cell lines verified the increased radioresistance in colorectal cancer cells that are associated with ERCC1 overexpression, and they confirmed a high correlation between ERCC1 levels and radiotherapeutic efficiency." (PMID 36230725, 2022). "In addition, the higher expression levels of the ERCC1 gene have been linked with poor response of FOLFOX-based chemoradiation in colorectal cancer and with the aggressiveness of esophageal cancer." (PMID 35955506, 2022). "In addition, the genotypes CC and TC in MLH3 rs108621 compared with TT allele and ERCC1 rs3212986 AA variant have predominantly enhanced the risk of colorectal cancer in males." (PMID 35330456, 2022). "A meta-analysis of 1787 gastric and colorectal cancer patients treated with oxaliplatin-based regimens found that ERCC1 rs11615C>T was associated with reduced response and poor survival in Asians, whereas ERCC2 rs13181T>G was associated with reduced response and poor survival in Caucasians." (PMID 30646508, 2019). "Interestingly, one recent study showed that ERCC1-C8092A SNP also was linked to increased risk of colorectal cancer in a Chinese population." (PMID 25191856, 2014).